AR (androgen receptor)
Diseases named in the same sentence as AR in open-access papers (continued):
Sharing a sentence is not in itself a finding about the gene and the disease.
prostate carcinoma (continued). "For example, it has been shown that AR can directly bind the enhancer element within the SOX2 promoter in prostate cancer cells, resulting in the inhibition of SOX2 transcription." (PMID 33420371, 2021). "The progression path indicates that most prostate cancers evolve from normal tissue by continuously increasing AR signaling (PC2)." (PMID 34857732, 2021). "Although current knowledge about lncRNAs in prostate cancer is expanding, numerous lncRNAs remain unidentified with respect to AR‐mediated regulation." (PMID 33219721, 2021). "The androgen receptor (AR) is the main driver of proliferation in prostate cancer (PCa) cells, and thus is an important therapeutic target." (PMID 33671614, 2021). "Given its integral metabolic functions, it is unsurprising that AR is the primary oncogenic driver of prostate cancer (PCa) and the major therapeutic target in advanced and metastatic disease." (PMID 34382934, 2021). "Androgen deprivation therapy using Bicalutamide or Enzalutamide, which are androgen receptor antagonists, are commonly used as a therapeutic drug for prostate cancers." (PMID 33669559, 2021). "Beyond chemotherapy, it is well known that the AR axis still plays an essential role in prostate cancer progression, despite the ensured castration state." (PMID 33557050, 2021). "Here, we demonstrate that inhibition of p38 MAPK decreases the growth and survival of prostate cancer cells that are dependent on AR signaling." (PMID 33671134, 2021). "This is in contrast with previous reports on prostate cancer cells, in which AR inhibition, while synthetically lethal with other treatments, does not appear to be sufficient to induce DNA damage and downstream events by itself." (PMID 33112375, 2021). "Data from prostate cancer research has demonstrated the androgen receptor as a regulator of TMPRSS2, capable of increasing the expression of this gene." (PMID 33179220, 2021). "In this study, we identified sense eRNAs and antisense eRNAs were regulated by androgen receptor (AR) activity in prostate cancer cells." (PMID 33408781, 2021). "AR antagonists including enzalutamide are available for treating prostate cancer patients in clinic and can pass the blood–brain barrier, thus are potentially good candidates for GBM treatment but have not been tested in GBM orthotopically." (PMID 34094902, 2021). "To further study the different direction of transcripts, we performed strand-specific, ribosome-minus RNA sequencing (RNA-seq) in AR positive prostate cancer cells." (PMID 33408781, 2021). "Our findings reveal the important role of ISL1 in androgen receptor (AR)-dependent prostate cancer cell growth; ISL1 knockdown reduced the AR activity and cell growth." (PMID 34753990, 2021). "In our previous studies we have shown that CYP3A5 expressed in intratumoral prostate regulates AR expression regulating prostate cancer cell growth." (PMID 34570813, 2021). "Androgen deprivation therapy (ADT) is a mainstay of prostate cancer treatment, given the dependence of prostate cells on androgen and the androgen receptor (AR)." (PMID 33513133, 2021). "The AR gene has been exogenously transduced into AR-negative prostate cancer cell lines to study the consequences of AR expression in this setting." (PMID 33420371, 2021). "Analyses of prostate cancer cell lines identified miR-141, miR-200a, miR-200b and miR-200c among many miRNAs that are upregulated upon stimulation of androgen receptor (AR) signaling by dihydrotestosterone and the synthetic androgen R1881." (PMID 34884985, 2021). "An earlier study suggested that USP12 deubiquitinates the androgen receptor to promote the AKT signaling pathway in prostate cancer." (PMID 33941870, 2021).
prostate carcinoma (continued). "In prostate cancer cells, the AR is responsible for activation of genes involved in cell proliferation and tumor progression." (PMID 34638309, 2021). "The growth and survival of prostate cancer cells are sustained by androgens through the activation of androgen receptor (AR) and its mediated signalings." (PMID 33750894, 2021). "While 1 nM of R1881 (an androgen mimetic) overcomes the effect of enzalutamide due to decreased drug target engagement, ARCC-4 still induces degradation of the androgen receptor to block prostate cancer cell growth even in the presence of 10 nM R1881." (PMID 33839157, 2021). "An acquired drug resistance occurs in prostate cancer after treatments with next-generation androgen receptor (AR) pathway inhibitors such as abiraterone and enzalutamide (ENZ)." (PMID 33572108, 2021). "Specifically, half of the “prostate cancer” pathway DEGsSD had previously been referred to in the literature (AR, CDKN1A, CTNNB1, EGFR, KLK2, NKX3-1, PDGFRA, SRD5A2)." (PMID 34768937, 2021). "The inhibition of the androgen receptor (AR) is an established strategy in prostate cancer (PCa) treatment until drug resistance develops either through mutations in the ligand-binding domain (LBD) portion of the receptor or its deletion." (PMID 33801338, 2021). "Collectively, these evidences suggested that U2AF65 functions as the “commander” role of AR splicing machinery and prostate cancer development." (PMID 33430885, 2021). "H2A was deubiquitinated by deubiquitinating enzyme USP16, and deubiquitinating of H2A is required for the activation of androgen receptor (AR)-mediated genes in prostate cancers." (PMID 34130705, 2021). "Although few reports describe the consequences of AR revival in prostate cancer cells, results seem to be concordant." (PMID 33420371, 2021). "In prostate cancer cells, androgens bind and activate the intracellular mediator called Androgen Receptor that control cell proliferation and survival." (PMID 33807106, 2021). "The androgen receptor (AR) signaling pathway plays an important role in the development of prostate cancer." (PMID 34295247, 2021). "The cell line CWR-R1 is a prostate cancer cell line that shows moderate sensitivity to the AR inhibitor enzalutamide, as compared to the sensitive LNCaP cells and resistant 22rv1 cells." (PMID 34211036, 2021). "Androgen receptor signaling primarily influences both the normal growth and proliferation of the prostate gland and the development of prostatic carcinoma." (PMID 33754118, 2021). "In AR-positive prostate cancer cells, CREB-binding protein (CBP), a histone acetyltransferase, has been shown to act as an AR coactivator in transcriptional activation of AR target genes." (PMID 34298822, 2021). "Prostate cancer (PC) is a multifactorial disease characterized by the abrogation of androgen receptor signaling." (PMID 33499881, 2021). "Peptidyl-prolyl isomerase Pin1 can hinder androgen receptor interaction with the β-catenin and modulate prostate cancer cell proliferation." (PMID 35201496, 2021). "Treatments of prostate cancer are currently focusing on targets downstream of the androgen receptor (AR) pathway such as prostate-specific membrane antigen (PSMA)." (PMID 34298682, 2021). "In prostate cancer cells, deacetylated Hsp90 binds to and stabilizes the androgen receptor (AR), while the HDAC6 suppressor sulforaphane led to increased levels of acetylated Hsp90 accompanied by enhanced AR degradation." (PMID 34959719, 2021). "An AR-SREBP1-6PGD axis influences prostate cancer cell growth and activity of the pentose phosphate pathway." (PMID 34382934, 2021). "Powerful drugs that block AR action by lowering androgen levels–so-called androgen deprivation therapy—are used to treat prostate cancer patients, and this yields initial success in reducing tumor growth." (PMID 33513133, 2021).
prostate carcinoma (continued). "This integrative functional genomics and clinical genomics filtering strategy revealed known prostate cancer-specific driver genes, AR and HOXB13, as the top two hits." (PMID 34326322, 2021). "Here, we identify a novel AR/AR-V7 degrader (ARVib) and found that ARVib effectively degrades AR/AR-V7 protein and attenuates AR/AR-V7 downstream target gene expression in prostate cancer cells." (PMID 34272475, 2021). "Androgen receptor (AR), an androgen-activated transcription factor, plays a pivotal role not only in normal development and growth of the prostate but also in prostate cancer (PCa) development and progression to castration-resistant prostate cancer (CRPC) 1-3." (PMID 33391515, 2021). "In prostate cancer, hnRNPK localisation was previously reported to regulate androgen receptor (AR) activity and prostate cancer prognosis." (PMID 33931969, 2021). "That said, the stronger inhibition of the AR signaling axis has led in recent years to an increase of prostate cancers that de-differentiate into AR-negative disease." (PMID 33420371, 2021). "AR is a well-established oncogenic driver and therapeutic target in prostate cancer, and the requirement of FOXA1′s pioneering function for AR activation and disease progression is well established." (PMID 34680352, 2021). "Despite advances in the development of highly effective androgen receptor (AR)-targeted therapies for the treatment of men with advanced prostate cancer acquired resistance ultimately ensues." (PMID 34099734, 2021). "We find that BRG1 promotes gene expression in prostate cancer models with varying degrees of dependence on AR and FOXA1." (PMID 33596994, 2021). "This was in comparison with both PSA and PSMA well-known prostate cancer markers, which were observed only in the LNCaP (AR expressing) and its lineage derivatives." (PMID 34099820, 2021). "The compounds also revert the proliferation of castrate-resistant prostate cancer cells, provided they express the androgen receptor." (PMID 34853378, 2021). "In the subsequent studies, they found another compound ARD-266, with an effective AR antagonist and a VHL ligand (weak binding affinity to VHL), also effectively induced AR protein degradation with a low DC50 value (0.2–1 nM) in prostate cancer cells." (PMID 34488823, 2021). "Metastatic prostate cancer is initially sensitive to androgen receptor inhibition, but eventually becomes castration-resistant prostate cancer (mCRPC)." (PMID 34568716, 2021). "We observed that bergamottin reduces prostate cancer (PC) cell growth by decreasing both total and nuclear AR (AR activation) reducing downstream AR signaling." (PMID 34570813, 2021). "In human prostate cancer cells, celastrol induces autophagy by targeting the androgen receptor (AR)/miR-101." (PMID 34575981, 2021). "Here, our results have demonstrated PRPF6 acts as a key regulator for action of both AR-FL and AR-V7, thereby participating in the enhancement of AR-FL and AR-V7-induced transactivation in prostate cancer." (PMID 33390843, 2021). "The glucocorticoid receptor (GR) is a prime suspect for acquired therapy resistance, as prostate cancer (PCa) cells are able to increase GR signaling during anti-androgen therapy and thereby circumvent androgen receptor (AR)-blockade and cell death." (PMID 33795839, 2021). "Intriguingly, MMP-1 had the ability to decrease AR signal and, concomitantly, enhance prostate cancer cell proliferation." (PMID 34966687, 2021). "Understanding the biological mechanisms of how bergamottin regulates AR signaling in prostate cancer patients can help establish its mechanism based role in blocking prostate cancer growth especially in AAs expressing high CYP3A5 to reduce health disparity." (PMID 34570813, 2021). "Because the AR pathway represents such a key therapeutic contact point in prostate cancer, researchers have set out to search for means to restore AR signaling in AR-negative prostate cancer." (PMID 33420371, 2021).
prostate carcinoma (continued). "The androgens testosterone (T) and dihydrotestosterone (DHT) are hormones that play an important role in the development of prostate cancer, while the androgen receptor (AR) is central to the clinical management of prostate cancer." (PMID 34885749, 2021). "FTO also contributed to enzalutamide resistance in castration-resistant prostate cancer by mediating alterations within androgen receptor-regulated enhancer RNAs (AR-eRNAs)." (PMID 33669361, 2021). "Several signaling pathways have been studied for decades in the context of their role in inducing or bypassing androgen receptor signaling in castration and/or treatment resistant prostate cancer." (PMID 33572108, 2021). "In this study, significantly increased expression of Skp2, AR, and Slug, along with E-cadherin downregulation, was observed in primary prostate cancer in patients who already had lymph node metastases." (PMID 33799604, 2021). "The high expression of androgens and androgen receptors (AR) is closely related to prostate carcinoma." (PMID 34568317, 2021). "Experiments in prostate cancer cells demonstrated binding of AR to BCLX promoter and AR-dependent regulation of BCLX expression." (PMID 33668112, 2021). "It is well known that prostate cancer can be easily affected by dihydrotestosterone (DHT) via androgen receptor (AR)." (PMID 33937049, 2021). "We previously reported that dietary WBM antagonized dihydrotestosterone (DHT)-induced androgen receptor (AR) activation and reduced myeloid-derived suppressor cells (MDSCs) in prostate cancer animal models and patients." (PMID 34341347, 2021). "When H4-pY88 epigenetic marks were reversed using an ACK1 inhibitor, this sensitized naïve and enzalutamide-resistant prostate cancer cells expressing reduced AR levels, leading to slowed CRPC tumor growth." (PMID 34930302, 2021). "Recently, it was shown that upregulation of MUC1-C in androgen-dependent prostate cancer cells leads to suppression of AR axis signaling and induces the neural BRN2 transcription factor." (PMID 33572108, 2021). "Several pieces of evidence from breast and prostate cancers show that AKT S473 can phosphorylate AR at S210/213." (PMID 34681618, 2021). "Understanding of the molecular mechanisms of prostate cancer has led to development of therapeutic strategies targeting androgen receptor (AR)." (PMID 34771580, 2021). "The vast majority of AR binding sites were shared among healthy prostate, primary prostate cancer, and metastatic tumor samples, signifying core AR‐driven transcriptional regulation within the prostate cell lineage." (PMID 33576154, 2021). "If overexpressed in prostate cancer cells, both of them can increase the expression of neuroendocrine markers and downregulate luminal markers, including AR." (PMID 33420371, 2021). "Androgens and Androgen receptor (AR) play a critical role in prostate cancer progression, while estrogen receptor deregulation is associated with breast cancer." (PMID 33915795, 2021). "For example, sintokamide A was one of the first natural products reported to block the NTD transactivation of the AR in prostate cancer cells." (PMID 33672769, 2021). "In fact, AR can enhance miR-525-5p transcription in prostate cancer, while decreasing its transcription in breast cancer by binding to different AREs in the precursor promoter of this miRNA." (PMID 34831421, 2021). "Prostate cells depend on androgens and the androgen receptor (AR) for growth and survival, and AR is a key driver of prostate cancer from early to late stage disease." (PMID 33513133, 2021).
prostate carcinoma (continued). "The work from Palvimo laboratory revealed that PIAS1 is a chromatin-bound AR coregulator that functions in a target gene selective fashion to regulate prostate cancer cell growth." (PMID 33572160, 2021). "It has also been shown that MRGBP accelerates androgen receptor-mediated transactivation and promotes the growth of androgen receptor-positive prostate cancer cells." (PMID 34660575, 2021). "The development and clinical success of more efficient AR signaling inhibitors come with the drawback of an increased prevalence of highly aggressive, AR-negative prostate cancer." (PMID 33420371, 2021). "The growth of prostate cancer cells depends on the androgen axis and the transcriptional activation of the androgen receptor (AR) by its natural ligands testosterone (T) or dihydrotestosterone (DHT)." (PMID 34298852, 2021). "Bone metastatic lesions derived from prostate cancers express high levels of Met, which are inversely correlated with the androgen receptor levels, and therefore related to the progression of the disease." (PMID 34572548, 2021). "The hyperactivity of androgen receptor (AR), a member of the nuclear receptor (NR) family of transcription factors, is the major driver of prostate cancer (PCa) progression to metastatic castration-resistant PCa or mCRPC." (PMID 33916325, 2021). "A proximity interaction network for the androgen receptor (AR) was obtained from androgen-responsive prostate cancer cells." (PMID 33640491, 2021). "Recently, it was shown that growth factor receptor-bound protein 10 (GRB10), has pro-proliferative function in prostate carcinoma, and that it sustains AR activity by interacting with PP2A." (PMID 33572160, 2021). "Another possible epigenetic effect of ATRA was tested using the androgen receptor (AR) in human prostate cancer." (PMID 34835969, 2021). "HOTAIR, a lncRNA, has been reported to enhance the androgen receptor-mediated transcriptional program and drive castration-resistant prostate cancer." (PMID 33808801, 2021). "The AR‐induced novel lncRNA named LINC00844 inhibits prostate cancer metastasis by increasing AR chromosome binding to induce NDRG1, a well‐known metastasis suppressor." (PMID 33219721, 2021). "Growth of prostate cancer (PC) is driven by androgens through activation of the androgen receptor and its target genes." (PMID 33921650, 2021). "Although MLK1 is tightly correlated with AR expression in a prostate cancer clinical dataset, we found that the inhibitory effects of the MLK1 inhibitor NSC14465 applied to, not only AR-positive, but also AR-negative, cell lines." (PMID 34439974, 2021). "Chemical or genetic inhibition of Dot1l impaired the viability of androgen receptor-positive prostate cancer cells." (PMID 33628364, 2021). "It was shown that there is an inverse correlation between the expression of IL-8 and AR in prostate cancer tissue." (PMID 34204596, 2021). "In conclusion, the findings by our group and others warrant further investigation of combined inhibition of the MAPK and AR pathway at an early stage of systemic treatment of AR-driven prostate cancer to overcome primary or acquired resistance." (PMID 34211036, 2021). "PC3 is a PTEN-negative prostate carcinoma cell line with constitutive activation of the PI3K-Akt ﻿pathway.﻿ LNCaP is an androgen receptor-positive and androgen-dependent growing prostate carcinoma cell line." (PMID 34321039, 2021). "In conclusion, AR-negative prostate cancer incidence will further rise as our ability increases to abrogate AR signaling." (PMID 33420371, 2021). "For example, a higher frequency of mutations in FOXA1, the gene encoding a pioneer factor that facilitates AR chromatin binding and transcriptional activation, was found in CRPC (12%) than in primary prostate cancer (4%)." (PMID 34630112, 2021). "Multiple studies have shown that TMPRSS2 is an androgen receptor (AR) target gene in prostate cancer cells." (PMID 34210968, 2021).